DCUN1D1 (defective in cullin neddylation 1 domain containing 1)
Description:
Part of an E3 ubiquitin ligase complex for neddylation. Promotes neddylation of cullin components of E3 cullin-RING ubiquitin ligase complexes. Acts by binding to cullin-RBX1 complexes in the cytoplasm and promoting their nuclear translocation, enhancing recruitment of E2-NEDD8 (UBE2M-NEDD8) thioester to the complex, and optimizing the orientation of proteins in the complex to allow efficient transfer of NEDD8 from the E2 to the cullin substrates. Involved in the release of inhibitory effets of CAND1 on cullin-RING ligase E3 complex assembly and activity. Also acts as an oncogene facilitating malignant transformation and carcinogenic progression (By similarity).
Synonyms: DCNL1; DCUN1L1; RP42; SCCRO; SCRO; Tes3
Tractability: Small molecule: a structure with a bound ligand is known; a high-quality ligand is known. PROTAC: UniProt records ubiquitination sites on it; ubiquitination databases record sites on it; its protein half-life has been measured; a small molecule that binds it is known.
Gene: Protein-coding gene on chromosome 3 (182,938,074 to 182,985,953, reverse strand). Ensembl gene ENSG00000043093.
Subcellular location: Nucleus; Cytoplasm
Subcellular location (Human Protein Atlas): Nucleoplasm; Cytosol
Pathways (Reactome):
Metabolism of proteins: Neddylation
Gene Ontology:
Molecular function: cullin family protein binding; protein binding; ubiquitin conjugating enzyme binding; ubiquitin-like protein binding
Biological process: positive regulation of protein neddylation; regulation of protein neddylation; regulation of protein ubiquitination; protein neddylation
Cellular component: cytoplasm; nucleus; ubiquitin ligase complex; cytosol
Genetic constraint (gnomAD): Loss-of-function variants: 2 observed, 11.9 expected, observed/expected ratio (o/e) 0.17, 90% interval 0.068 to 0.53. The upper end of that interval is the gene's LOEUF score, 0.53, which puts it in group 2 of 6, group 1 being the genes least tolerant of losing a copy. Missense variants: 68 observed, 148.7 expected, observed/expected ratio (o/e) 0.46, 90% interval 0.38 to 0.56. Synonymous variants: 41 observed, 50.2 expected, observed/expected ratio (o/e) 0.82, 90% interval 0.63 to 1.06.
Homologues: Orthologues: chimpanzee DCUN1D1 (100% identical), dog DCUN1D1 (100% identical), rabbit DCUN1D1 (99% identical), mouse Dcun1d1 (99% identical), rat Dcun1d1 (98% identical), mouse Tes3-ps (98% identical), tropical clawed frog dcun1d1 (98% identical), guinea pig Dcun1d1 (97% identical), macaque DCUN1D1 (94% identical), zebrafish dcun1d1 (89% identical), Drosophila melanogaster SCCRO (63% identical), Caenorhabditis elegans dcn-1 (41% identical), and 1 more. Paralogues in human: DCUN1D2 (78% identical), DCUN1D3 (39% identical), DCUN1D4 (31% identical), DCUN1D5 (28% identical).